SKP2 (S-phase kinase associated protein 2)
Diseases named in the same sentence as SKP2 in open-access papers (continued):
Sharing a sentence is not in itself a finding about the gene and the disease.
hepatocellular carcinoma (38 papers, 2009 to 2026). A malignant tumor that arises from hepatocytes. "In this context, Lee and colleagues demonstrated that polyubiquitination of LKB1 by S-Phase Kinase-Associated Protein 2 (Skp2) ubiquitin ligase promotes its persistent activation, leading to cell survival and poor outcome in hepatocellular carcinoma patients." (PMID 31781355, 2019). "Mounting evidence indicates that S-Phase Kinase-Associated Protein 2 (SKP2) is overexpressed in human hepatocellular carcinoma (HCC)." (PMID 25537506, 2015). "Additionally, Sja-miR-7-5p, an miRNA derived fromS. japonicum, has been shown to exhibit antitumor activity against hepatocellular carcinoma during schistosome infection by inhibiting the expression of S-phase kinase-associated protein 2 that promotes the viability and migration of tumor cells." (PMID 39314046, 2024). "This post-translational modification enhances SKP2 stability and E3 ligase activity, promoting p21/p27 degradation and accelerating the G1-S phase transition, thereby driving hepatocellular carcinoma (HCC) cell proliferation." (PMID 40809696, 2025). "In hepatocellular carcinoma cells, SHIP2 accumulates polyubiquitination due to its interaction with S-phase kinase-associated protein 2 (SKP2), a component of the E3 ubiquitin ligase complex." (PMID 38200519, 2024). "PRI-724 significantly increased the percentage of hepatocellular carcinoma cells in the G0/G1 cell cycle phases and induced G0/G1 arrest, along with an increase in p21 Waf1/Cip1 expression and a reduction in c-Myc and Skp2 expression." (PMID 37763649, 2023). "In hepatocellular carcinoma, Skp2 was identified at a significantly increased level compared with paired normal tissue, and was correlated with tumor grade, size, and metastases." (PMID 32165861, 2020). "The phenotypes of the cells treated with SKP2 siRNA were similar to those of sja-miR-7-5p mimics-treated cells, which suggested that the inhibitory effects of the schistosome miRNA on hepatoma cells function by downregulating SKP2 expression." (PMID 30967999, 2019). "The secreted Wnt7a inactivated SKP2 leading to upregulation of P21, which inhibits the growth of hepatocellular carcinoma." (PMID 31886205, 2019). "It was reported that in hepatocellular carcinoma, loss of KIF14 downregulates the expression of Skp2 and Cks1, leading to accumulation of p27Kip1." (PMID 28525372, 2017). "For example, in HepG2 human hepatoma cells, Skp2 induces cell cycle progression via the activation of c-Myc transcriptional activity and independently of p27kip1 expression." (PMID 27380896, 2016). "Overexpression of SKP2, a positive regulator of G1-to-S phase transition, has been observed in numerous cases of human cancer, including hepatocellular carcinoma (HCC)." (PMID 25310357, 2014). "Moreover, the downregulation of SHIP2 by Hepatitis B Virus X promotes cell migration and induces resistance to 5-Fluorouracil (5-FU) in hepatocellular carcinoma through SKP2." (PMID 38200519, 2024). "Over-expressed Skp2 confers troglitazone resistance in hepatoma cells." (PMID 34068643, 2021). "In addition, transfection of the hepatoma cells with the murine Skp2 siRNA generated a similar outcome to that in cells transfected with sja-miR-7-5p mimics." (PMID 30967999, 2019). "Although both Skp2 and Psme3 genes were validated as target gene by luciferase reporter assay, our experimental data with Skp2 and Psme3 siRNA showed that only the hepatoma cell transfected with the Skp2 siRNA produced similar phenotype to that of sja-miR-7-5p mimics-treated cells." (PMID 30967999, 2019). "In the present study, we found that in liver cancer cells, including Hepa1-6 cells and HepG2 cells, sja-miR-7-5p inhibited the growth and migration of both mouse and human hepatoma cells by targeting SKP2 to elevate the expression of P27 and decrease the expression of MMP9." (PMID 30967999, 2019).
hepatocellular carcinoma (continued). "Therefore, our data demonstrated that sja-miR-7-5p suppresses hepatoma cell growth and migration by downregulating SKP2." (PMID 30967999, 2019). "SKP2 promotes HCC (hepatocellular carcinoma) progression and its autophagy-induced nuclear function via CARM1 and AMPK." (PMID 38020920, 2023). "In addition, miR-340 displayed antineoplastic functions via suppressing Skp2 in liver carcinoma." (PMID 33621206, 2021). "In hepatocellular carcinoma (HCC), miR-340 inhibits cell proliferation and tumor growth by inhibiting SKP2 expression 47, and regulating the JAK1/STAT3 pathway." (PMID 33390846, 2021). "Skp2-dependent ubiquitination and activation of LKB1 in hepatocellular carcinoma cells is essential for cancer cell survival under energy stress." (PMID 32357935, 2020). "In hepatocellular carcinoma cells, E2F1 promotes cell proliferation and suppresses apoptosis by inducing c-Myc expression and upregulating SKP2 expression." (PMID 31327760, 2019). "Whereas, it has been reported that Numb promotes cell proliferation and cell cycle of hepatocellular carcinoma, inhibiting p21 and modulating CDK4 and SKP2." (PMID 30034624, 2018). "A recent research indicated that SKP-2, an oncogenic subunit of an ubiquitin ligase complex, which founctions as a critical regulator of S phase progression, could promote degradation of RASSF1A at the G1/S checkpoint and then lead to the cell cycle proceeding in hepatocellular carcinoma." (PMID 20042089, 2009).
melanoma (38 papers, 2011 to 2025). A malignant, usually aggressive tumor composed of atypical, neoplastic melanocytes. "Transcriptional factors like Ap-1 and NF-kB and activation of the MAPK pathway and S-phase kinase-associated protein 2/Skp2/MTH1 axis have been implicated in protecting melanomas from ROS damage." (PMID 37297001, 2023). "Similar to loss of p27, increased Skp2 expression levels are also correlated with poor prognosis of patients with melanoma." (PMID 25593992, 2014). "Since previous study showed that nuclear Skp2 expression was associated with melanoma patient survival, we also examined the correlation between nuclear Skp2 expression and patient survival." (PMID 21386910, 2011). "The log-rank test and univariate Cox regression analyses revealed that both AJCC stages and cytoplasmic Skp2 expression were significantly associated with overall or disease-specific survival in all melanoma patients." (PMID 21386910, 2011). "In primary melanoma patients, age, tumor thickness, ulceration and cytoplasmic Skp2 expression were all significantly associated with both overall and disease-specific survival." (PMID 21386910, 2011). "Our study showed that cytoplasmic Skp2 expression was increased in melanoma, which may be due to BRAF mutation." (PMID 21386910, 2011). "Since cytoplasmic Skp2 was associated with melanoma patient survival, we next examined whether cytoplasmic Skp2 expression is an independent prognostic marker for melanoma patient survival by multivariate Cox proportional hazard analysis." (PMID 21386910, 2011). "Next, we separated all melanoma (n = 392) into primary melanoma (n = 259) and metastatic melanoma (n = 133) and found cytoplasmic Skp2 expression was associated with overall (P = 0.025) and disease-specific five-year survival (P = 0.018) in primary melanoma patients." (PMID 21386910, 2011). "Overexpression of Skp2 has been shown to increase lung vascular permeability and promote lung metastasis of B16 melanoma cells." (PMID 40534867, 2025). "On the other hand, MTH1 is ubiquitinated by an E3 ligase SKP2 in melanoma cells, which plays an oncogenic role." (PMID 39075342, 2024). "Skp2 was found to over-express in vemurafenib-resistant melanoma cells, and the stability of Skp2 was related to the drug-resistant mechanisms." (PMID 37089937, 2023). "miR-590-5p has been found to suppress malignant melanoma cell growth and invasions by targeting Skp2 and downregulation of circ-PITHD1 can inhibit colorectal cancer through suppression and the miR-590-5p/HK2 axis." (PMID 37540226, 2023). "For example, the expression and stability of Skp2 protein was reported to relate to the vemurafenib-resistance in melanoma cells." (PMID 37089937, 2023). "Inhibition of Skp2 expression can effectively inhibit the proliferation and invasion of melanoma cells." (PMID 35845132, 2022). "miR-590-5p is underexpressed in melanoma cells, and its overexpression can inhibit Skp2 expression and proliferation and invasion of melanoma cells." (PMID 35845132, 2022). "SKP2 is classically considered an oncogene, as it is amplified and overexpressed in various cancer contexts, including breast, T-cell lymphoma, melanoma, and Kaposi’s sarcoma." (PMID 36496990, 2022). "In melanoma cells, Skp2 has been shown to increase expression in melanoma cells, affecting patient survival." (PMID 35845132, 2022). "In this study, we found that miR-590-5p can inhibit the proliferation of melanoma cells and induce their apoptosis by targeting Skp2 expression." (PMID 35845132, 2022). "Previous literature have shown that Skp2 expression is upregulated in multiple cancer cells, so we transfected Skp2 siRNA into melanoma cells to knock down Skp2 expression." (PMID 35845132, 2022). "The results indicate that Skp2 is highly expressed in melanoma cells and inhibits the proliferation and invasion of melanoma cells." (PMID 35845132, 2022).
melanoma (continued). "The expression level of Skp2 in different malignant melanoma cell lines was higher than that in normal melanocytes." (PMID 35845132, 2022). "Subsequently, immunohistochemical results showed that Skp2 was significantly expressed in melanoma nuclei." (PMID 35845132, 2022). "Skp2 is also highly expressed in melanoma tissues and BRAFV600E inhibitor vemurafenib suppressed Skp2 expression and cell growth." (PMID 34068643, 2021). "Skp2 depletion in melanoma cells resulted in a G2-M phase arrest, and suppression of both BRAF (V600E) and Skp2 inhibited cell growth and invasion in melanoma cell lines." (PMID 33841154, 2021). "In melanomas, similar to Cks1, increasing expression of Skp2 with melanocytic tumor development from nevi to primary and metastatic melanomas was also demonstrated." (PMID 29423113, 2018). "The knockdown of Skp2 led to the accumulation of p27Kip1 and the impaired proliferation of melanoma cells in vitro." (PMID 28544818, 2017). "Skp2 depletion in melanoma cells and mouse embryonic fibroblasts (MEFs) results in G2M arrest and accumulation of polyploid cell forms." (PMID 28335434, 2017). "We also have examined the effect of FKA on Skp2 expression and Cullin1 NEDDylation in different cancer cell lines, including prostate, breast, renal, liver, lung, colon and cervical cancers, melanoma and osteosarcoma." (PMID 26497688, 2015). "Strikingly, treatment of melanoma cells with 10058-F4 efficiently diminished EMT mediated by TGF-β and S-phase kinase-associated protein 2 (SKP2)." (PMID 25883651, 2015). "Decreases in p27 levels occur via increased proteosomal degradation, especially that governed by the Skp2 pathway, which is consistent with the inverse correlation of p27 and Skp2 expression levels that has been reported in human melanomas." (PMID 25593992, 2014). "We found low expression of nuclear Skp2 in oral nevi compared to melanomas, confirming an oncogenic potential of Skp2." (PMID 23385514, 2013). "The epithelial cells of the normal oral mucosa in nevi and melanomas showed Skp2 protein positivity restricted to the nuclei of basal epithelial cells, together with some cells in the immediate suprabasal layers, serving as an internal positive control." (PMID 23385514, 2013). "Our previous studies found that 12 markers including pAkt, Bim, BRG1, BRMS1, CTHRC1, Cul1, ING4, MCL1, NQO1, SKP2, SNF5 and SOX4 were associated with melanoma progression." (PMID 23028750, 2012). "To further examine the role of Skp2 subcellular expression in melanoma development and its prognostic significance, we evaluated both nuclear and cytoplasmic staining in 30 normal nevi, 61 dysplastic nevi, 290 primary melanomas and 146 metastatic melanomas." (PMID 21386910, 2011). "Since cytoplasmic Skp2 expression was correlated with melanoma progression, we next examined the correlation between cytoplasmic Skp2 expression and different clinicopathologic characters." (PMID 21386910, 2011). "This study demonstrates that cytoplasmic Skp2 plays an important role in melanoma pathogenesis and its expression correlates with patient survival." (PMID 21386910, 2011). "In melanoma, however, the prognostic significance of subcellular Skp2 expression remains controversial." (PMID 21386910, 2011). "Increased cytoplasmic Skp2 expression was correlated with ulceration of melanoma (P = 0.005, χ2 test)." (PMID 21386910, 2011). "In melanoma cells, mutation in BRAF constitutively activates BRAF signaling, which regulates Cks1/Skp2-mediated p27 degradation and controls G1 cell cycle event." (PMID 21386910, 2011). "Skp2 regulates invasive ability of melanoma cells and overexpression of Skp2 correlates with advanced melanoma." (PMID 21386910, 2011). "Significant differences for Skp2 staining were observed between normal and dysplastic nevi (P = 0.039, χ2 test), dysplastic nevi and primary melanoma (P = 0.008, χ2 test), and primary and metastatic melanoma (P = 0.008, χ2 test)." (PMID 21386910, 2011).
melanoma (continued). "Various levels of cytoplasmic and nuclear Skp2 staining were observed in nevi and melanoma biopsies." (PMID 21386910, 2011). "In primary melanoma, we found a correlation between the depth of tumor invasion (thickness), ulceration and cytoplasmic Skp2 expression in the primary melanoma, which suggests a role of Skp2 in tumor invasion." (PMID 21386910, 2011). "We found that cytoplasmic Skp2 expression is increased in melanoma and the increased cytoplasmic Skp2 expression correlated with melanoma development." (PMID 21386910, 2011). "There are differences in the pattern of cytoplasmic Skp2 expression in melanocytic lesions at different stage, with increased levels of expression from normal nevi to dysplastic nevi and melanoma." (PMID 21386910, 2011). "In primary melanoma, high cytoplasmic Skp2 expression was found in 58% of tumors with thickness >2.00 mm, compared to 33% of melanomas with thickness ≤2.00 mm (P<0.001, χ2 test)." (PMID 21386910, 2011). "Conversely, miR-30-dependent repression of Skp2 may play a critical role in suppressing lung metastasis in melanoma patients, highlighting its potential as a therapeutic target." (PMID 40534867, 2025). "As Skp2 was reported to correlate with poor outcome in BRAFV600E other than BRAFWT melanomas, targeting Skp2 might be promising in the treatment of BRAFV600E melanomas." (PMID 37089937, 2023). "In addition, the combination of tubulin inhibitor VERU-111 and vemurafenib also inhibited vemurafenib-resistant melanoma effectively by inhibiting tubulin protein and Skp2 protein together." (PMID 37089937, 2023). "The Skp2 expression is upregulated in melanoma cells and tissues, suggesting that Skp2 may be involved in the development of malignant melanoma cells." (PMID 35845132, 2022). "First, we examined Skp2 expression level in malignant melanoma." (PMID 35845132, 2022). "Pharmacological inhibitors for FER and SKP2 are available, and further investigation is needed to study their roles in acral and mucosal melanomas and determine whether they constitute therapeutic targets." (PMID 35706047, 2022). "Therefore, targeted inhibition of Skp2 expression can regulate the proliferation of melanoma, which can be used as a new idea for the treatment of melanoma." (PMID 35845132, 2022). "Therefore, this study combined genes with miRNA to explore the effects of Skp2 and miR-590-5p on melanoma cells and the mechanism of Skp2 action." (PMID 35845132, 2022). "Skp2 expression can promote the growth and invasion of melanoma cells." (PMID 35845132, 2022). "miR-590-5p inhibits Skp2 expression and inhibits melanoma cell development, while overexpression of Skp2 could reverse the inhibitory effect of miR-590-5p." (PMID 35845132, 2022). "SKP2 is frequently overexpressed in melanoma and other cancer types." (PMID 35706047, 2022). "In this study, we found that both miR-590-5p and Skp2 were abnormally expressed in melanoma cells." (PMID 35845132, 2022). "This suggests that both miR-590-5p and Skp2 are involved in the treatment of malignant melanoma." (PMID 35845132, 2022). "In malignant melanoma, Skp2 is highly expressed and correlates with tumor malignancy." (PMID 33841154, 2021). "Interestingly, one study revealed that the level of SKP2 was elevated by TGF-β1 treatment in human melanoma, which was accompanied by increased phosphorylation of Akt1 and accumulation of c-Myc during EMT." (PMID 30999935, 2019). "Importantly, earlier work on correlations between the pathological and immunohistochemical profiles in melanomas found that Skp2 cytoplasmic levels correlated with aggressive melanomas and predicted poorer 10-year survival rate." (PMID 29423113, 2018). "These genes included SKP2, TOP2A, SOX4, MAP2 and CTLA4, all of which have been associated with patient outcome in melanoma." (PMID 29193607, 2018).